GLS (glutaminase)
Diseases named in the same sentence as GLS in open-access papers (continued):
Sharing a sentence is not in itself a finding about the gene and the disease.
breast tumor (14 papers, 2011 to 2025). "We also show that GLS protein levels are increased in aggressive human breast tumors and lower DFS for endocrine therapy." (PMID 31428575, 2019). "Indeed, GLS inhibition sensitizes breast tumours to CDK4/6 and PRAP inhibition and overcomes breast tumour resistance to mTOR inhibitors." (PMID 34572926, 2021). "Moreover, glutamine independence of breast tumor cells with a luminal phenotype was associated with elevated expression of glutamine synthetase (GLUL) and reduced glutaminase (GLS) levels." (PMID 29434187, 2018). "SLC1A5, GLS, PYCR1 and PIK3CA were significantly expressed in breast tumours with high expression of SLC7A5 (p < 0.001), while the low expression of SLC7A5 was associated with high levels of p-mTORC1 (p < 0.001)." (PMID 29566741, 2018). "SLC7A5, SLC1A5, GLS and PIK3CA were significantly expressed in breast tumours with high expression of SLC3A2 (p < 0.001), while the low expression was associated with high levels of p-mTORC1 (p < 0.001)." (PMID 29545595, 2018). "This concordance indicates the differential expression of GLUL, GLS and GLS2 in the luminal and basal-type cancer cell lines reflects similar systematic differences in primary breast tumors." (PMID 21852960, 2011). "In a breast tumor expression dataset, we found significantly different expression levels of GLUL, GLS and GLS2 in the corresponding luminal (luminal A and B) and basal-types of breast tumors." (PMID 21852960, 2011). "The findings highlighted the importance of GLS in breast tumour proliferation and invasiveness and could potentially be used as a target for inhibition via the potent and non-competitive allosteric GLS inhibitor CB−839 (telaglenastat)." (PMID 34439127, 2021).
lymphoma (14 papers, 2016 to 2025). A malignant (clonal) proliferation of B- lymphocytes or T- lymphocytes which involves the lymph nodes, bone marrow and/or extranodal sites. "Researchers have found that c-Myc increases GLS expression through transcriptionally inhibiting miR-23a/b of the GLS 3′ untranslated region, leading to a greater expression of its target protein mitochondrial glutaminase in human lymphoma cells and PCa cells." (PMID 37190313, 2023). "The pharmacological blockade of these transporters (e.g., GPNA, V-9302) or inhibition of glutaminase (GLS), a key enzyme in glutamine catabolism (e.g., CB-839), has demonstrated anti-tumor efficacy in lymphoma models." (PMID 40806636, 2025). "Furthermore, in a lymphoma xenograft model, HP-MR using pyruvate evaluated the LDH-A and glutaminase (GLS) inhibition by small molecule drugs FX11 and BPTES [bis-2-(5-phenylacetamido-1,2,4-diathiazol-2-yl) ethyl sulfide] respectively." (PMID 30978984, 2019).
renal cell carcinoma (14 papers, 2019 to 2025). "Renal cell carcinoma (RCC) tumors express high levels of glutaminase (GLS), the enzyme required for the first step in metabolic conversion of glutamine to glutamate and the entry of glutamine into the TCA cycle." (PMID 34731180, 2021). "A novel small molecule that inhibits glutaminase isoforms not commonly expressed in normal cells is under study in two phase II trials (NCT03163667 and NCT03428217) for advanced renal cell carcinoma." (PMID 34638444, 2021).
lung adenocarcinoma (13 papers, 2016 to 2025). A carcinoma that arises from the lung and is characterized by the presence of malignant glandular epithelial cells. "Taken together, our data suggests that glutaminase is an attractive target in both lung adenocarcinoma and in other cancers in which the KEAP1/NRF2 axis is mutated and the glutaminase inhibitor CB-839 could be an effective therapeutic agent in patients with these genetic subtypes of cancer." (PMID 28967864, 2017). "A metabolic requirement for glutaminolysis in KEAP1-NRF2-mutant lung adenocarcinoma has been observed, and treatment with two glutaminase inhibitors greatly reduced growth potential." (PMID 34573012, 2021). "However, the precise mechanisms through which GLS modulates radiosensitivity and irradiation-induced immune responses in lung adenocarcinoma (LUAD) and its clinical value remain to be fully elucidated." (PMID 40308578, 2025). "Importantly, KEAP1/KRAS-mutant lung adenocarcinomas are dependent upon increased glutaminolysis and are therapeutically sensitive to pharmacologic inhibition of glutaminase." (PMID 30060526, 2018). "Interestingly, Best and colleagues showed that murine models of lung adenocarcinoma harboring KRAS and LKB1 mutations exhibit increased glutaminase expression by tumor cells and increased glutamate in the tumor microenvironment, compared to KRAS mutant/KEAP1 mutant lung adenocarcinomas." (PMID 40255421, 2025). "Targeting glutaminase 3’‐UTR with hsa‐miR‐1‐3p and overexpressing it reduces lung adenocarcinoma cell viability and invasion." (PMID 38717954, 2024).
neuroblastoma (13 papers, 2015 to 2024). Neuroblastoma (NB) is the most common solid, extracranial childhood tumor. "High GLS2 expression was significantly correlated with poor survival, while GLS expression was negatively associated with the prognosis of neuroblastoma patients." (PMID 38067269, 2023). "We tested this possibility by treating a panel of neuroblastoma cell-lines with the GLS inhibitor CB-839." (PMID 39313128, 2024). "The acute mitochondrial response of the neuroblastoma cells to Glutaminase 1 (GLS1) inhibitor BPTES, which inhibits the oxidation of L-glutamine leading to a L-glutamate deficiency, led to a decrease of the mitochondrial respiration rate, averaging −1.5 pmol/min for SH-SY5Y cells." (PMID 38668316, 2024). "In agreement with our results, previous studies have reported that enhanced c-Myc and N-Myc expression makes neuroblastoma and B-cells addicted to glutamine and suppression of glutamine metabolism, by inhibition of IDH1, IDH2 or GLS expression reduces cellular proliferation and tumor growth." (PMID 28430666, 2017). "Although c-MYC has been shown to regulate GLS expression via miR-23, we note that miR-23 levels are not significantly different in a comparison of MNA and non-MNA neuroblastomas." (PMID 39313128, 2024). "The induction of MYCN expression in SHEP MYCN-ER neuroblastoma cells, which carry a single copy of the MYCN gene, led to a time-dependent activation of GLS2 but not GLS." (PMID 38067269, 2023).
pancreatic ductal adenocarcinoma (13 papers, 2020 to 2025). An infiltrating adenocarcinoma that arises from the epithelial cells of the pancreas. "For example, succinylation at K311 of glutaminase (GLS-K311succ) enhances its activity, offsetting oxidative stress while promoting tumor cell survival and growth pancreatic ductal adenocarcinoma (PDAC)." (PMID 38882606, 2024). "In preclinical tumour models of pancreatic ductal adenocarcinoma glutaminase inhibition effectively targeted proliferating tumour cells, but was ineffective against the hypoxic subpopulation of cells." (PMID 32450839, 2020). "For example, upon glutaminase (GLS) inhibition in pancreatic ductal adenocarcinoma (PDAC) cells, the upregulation of pyruvate carboxylase (PC), activation of lipid biosynthetic pathways, and alternative pathways involved in glutamate production allowed cells to adapt and regain proliferation." (PMID 37720350, 2023). "On the other hand, posttranslational modification is critical to modulate enzyme activities and metabolic adaptation, epitomised where GLS1‐K311 succinylation is enhanced in human pancreatic ductal adenocarcinoma, supporting that GLS lysine modification is involved in carcinogenesis." (PMID 35538890, 2022). "Lu found that Glutaminase (GLS) was highly expressed in pancreatic ductal adenocarcinoma." (PMID 36308411, 2022). "For example, in pancreatic ductal adenocarcinoma (PDAC), SUCLA2-dependent succinylation of glutaminase (GLS) enhances NADPH and glutathione (GSH) production, improving redox balance and promoting survival." (PMID 40931345, 2025). "A recent study reported that GLS1 is overexpressed in human pancreatic ductal adenocarcinoma (PDAC) and SUCLA2 mediated succinylation of GLS (K311) could eliminate oxidative stress." (PMID 35366902, 2022). "A recent study showed that in pancreatic ductal adenocarcinoma (PDAC), activated GLS increased glutamine catabolism and production of nicotinamide adenine dinucleotide phosphate (NADPH) and glutathione, which prevented from being oxidative and promoting tumor cell survival and tumor growth in mice." (PMID 36620594, 2022).
acute myeloid leukemia (12 papers, 2016 to 2024). Acute myeloid leukemia (AML) is a group of neoplasms arising from precursor cells committed to the myeloid cell-line differentiation. "It has been shown that knockdown of the GLS-1 gene in acute myeloid leukemia (AML) cell lines disrupted glutamine-driven OXPHOS, resulting in reduced cell proliferation and the induction of apoptosis." (PMID 37228498, 2023). "Indeed, the removal of glutamine from cultures, knocking down glutamine transporters, and pharmacologically inhibiting GLS in acute myeloid leukemia reduce leukemic cell proliferation while increasing apoptosis." (PMID 37249600, 2023). "We also tested the effect the GLS inhibitor CB-839 had on pyruvate to lactate conversion in an acute myeloid leukemia (AML) animal model." (PMID 30978984, 2019). "CB-839 is a novel, potent, orally bioavailable GLS inhibitor that has been reported to have antiproliferative activity in a panel of triple negative breast cancer cell lines and most recently in acute myeloid leukemia (AML)." (PMID 27806325, 2016). "In a mouse model of acute myeloid leukemia (AML), blocking glutamine metabolism with a glutaminase inhibitor (CB-839) significantly impaired antioxidant glutathione production in multiple types of AML, leading to an increase in mitochondrial reactive oxygen species (mitoROS) and apoptosis." (PMID 35444235, 2022).
multiple myeloma (11 papers, 2017 to 2025). "Considering this finding, we conducted a study to assess the influence of CB-839, an oral medication that potently and specifically inhibits GLS, and analyzed its effect on myeloma cell activity." (PMID 39050886, 2024). "In conclusion, our findings underscore the critical role of glutaminolysis in myeloma cell proliferation and highlight the efficacy of GLS inhibitors in targeting myeloma cells while enhancing the cytotoxic effects of HDAC inhibitors." (PMID 39050886, 2024). "c-Myc is an important factor, which contributes to the tumorigenic phenotype of myeloma cells and increases glutamine transporters and glutaminase (GLS) expression to favor glutaminolysis." (PMID 33520703, 2020). "Here we show that the small molecule inhibitor compound 968 effectively inhibits glutaminase and that this inhibition induces apoptosis in both human multiple myeloma cell lines (HMCLs) and primary patient material." (PMID 29156762, 2017). "In addition to glucose as an energy source, myeloma cells consume a sizable amount of glutamine (Gln) via a process known as glutaminolysis, which converts Gln to glutamate (Glu) via glutaminase (GLS1)." (PMID 40721650, 2025). "Furthermore, our results suggest the clinical relevance of GLS inhibitors as potential drug candidates for the treatment of refractory myeloma." (PMID 39050886, 2024). "In addition, we analyzed the ability of CB-839 (telaglenastat), a glutaminase (GLS) inhibitor, to suppress myeloma cell proliferation and enhance the sensitivity to histone deacetylase (HDAC) inhibitors." (PMID 39050886, 2024). "CB-839 (glutaminase inhibitor, inhibiting recombinant GLS with an IC50 ∼30 nM) exhibited an anti-proliferative IC50 <100 nM in vitro across 36 of the cell lines, whilst twice daily CB-839 dosing also resulted in a 71% decrease of RPMI-8226 (multiple myeloma) tumor volume." (PMID 29050199, 2017).
bladder cancer (9 papers, 2015 to 2025). "Recent studies found that lincRNA-p21 can inhibit bladder cancer proliferation by negatively regulating glutaminase, glutamate, and α-ketoglutarate expression." (PMID 38544804, 2024). "Glutaminase metabolism, mediated by glutaminase 1 (GLS1), contributes to the tumor‐promoting phenotypes induced by circTRPS1 in bladder cancer." (PMID 39611045, 2024). "In bladder cancer tissues the lincRNA-p21 expression is significantly decreased, while glutaminase mRNA level is increased compared to normal tissues." (PMID 38544804, 2024). "Additionally, the abundance of lincRNA-p21 and glutaminase dictates the response of bladder cancer cells to BPTES (glutaminase inhibitor) treatment." (PMID 38544804, 2024). "Overexpression of glutaminase rescued inhibitory nature of lincRNA-p21 on bladder cancer survival." (PMID 38544804, 2024). "For example, GLS plays an important role in cell growth and energy metabolism during cancer stage progression, while HMGB3 promotes cell proliferation and migration and is associated with poor prognosis in urinary bladder cancer." (PMID 26179909, 2015).
cervical cancer (9 papers, 2017 to 2025). A primary or metastatic malignant neoplasm involving the cervix. "Evidence for an effect of metformin on glutaminase (GLS) expression was collected in cervical cancer cell lines as well, possibly as an effect of c-MYC downregulation by the drug." (PMID 33182253, 2020). "Various genes, namely GLS, CD36, WNT5a, HRAS, DDB2, PIK3R2, and CDH2 were found to be differentially highly expressed in primary cervical cancer samples of patients who developed distant recurrence." (PMID 35087740, 2021). "But based on our previous studies, we found that induction of glutaminase increased the level of glutathione and NADPH, and decreased the production of ROS in cervical cancer cells." (PMID 30674873, 2019). "Measuring the expression of GLS and PIK3R2 in the resected cervical cancer samples may be a future step in the identification of patients with a high risk of recurrence." (PMID 35087740, 2021). "Namely, GLS, CD36, WNT5a, HRAS, DDB2, PIK3R2, and CDH2 were significantly DE between cervical cancer without recurrence and cervical cancer with distant recurrence." (PMID 35087740, 2021).
developmental delay (9 papers, 2021 to 2025). "Glutaminase loss of function caused by duplication or tandem repeats reported ataxia, optic atrophy, developmental delay, and progressive neurological deterioration in childhood." (PMID 39559284, 2024). "Milder genetic changes in GLS gene with loss of function caused by tandem repeat changes of the noncoding area led to early‐onset developmental delay, ataxia, cerebellar atrophy, and gradual neurological deterioration in early childhood." (PMID 39559284, 2024). "Initial ES only uncovered one heterozygous and damaging variant in GLS in two probands who presented with global developmental delay, progressive ataxia, and elevated glutamine (GDPAG; OMIM #618412)." (PMID 36672937, 2023). "Of those remaining, the largest number of calls with predicted expansions were the ones in DMPK (myotonic dystrophy), GLS (global developmental delay, progressive ataxia and elevated glutamine) and HTT (Huntington disease)." (PMID 40004498, 2025). "Two de novo gain-of-function mutants of GLS, S482C and H461L, were recently identified in patients with developmental delay, epilepsy, and infantile cataract." (PMID 41000630, 2025). "In this study, we examined the enzymatic properties of the S482C and H461L GLS mutants discovered in two patients that exhibit high concentrations of glutamate in the brain, neurological disease, and developmental delay." (PMID 41000630, 2025). "Glutaminase (GLS) hyperactivity was first described in 2019 in a patient with profound developmental delay and infantile cataract." (PMID 37151363, 2023). "Glutaminase hyperactivity caused by heterozygous mutations was noticed to have profound developmental delay without dysmorphism, infantile cataract, and erythematic subcutaneous nodules." (PMID 39559284, 2024). "GLS loss‐of‐function [OMIM #618328/618412] due to biallelic variants was found in a total of nine patients from six unrelated families, with elevated glutamine plasma levels and a phenotypic spectrum of ataxia, optic atrophy, developmental delay, neonatal seizures, and neonatal death." (PMID 37151363, 2023). "Glutaminase hyperactivity has led to progressive developmental delay in children, and cataract, no dysmorphic features, generalized tonic–clonic seizures, and magnetic resonance spectroscopy have shown higher glutamate/glutamine ratio." (PMID 39559284, 2024). "Finally, noncoding expansions in GLS (glutaminase, MIM #138280) in patients with global developmental delay, progressive ataxia, and elevated plasma glutamine (GDPAG, MIM #618412) were identified thanks to their associated biochemical phenotype." (PMID 38835438, 2021).
Hyperammonemia (9 papers, 2008 to 2025). An increased concentration of ammonia in the blood. "The search for new sources of L-asparaginase is an imperative task to address the adverse effects caused by the secondary activity of glutaminase, which can lead to hyperammonemia due to the excessive accumulation of ammonia in the body from glutamine hydrolysis." (PMID 41202085, 2025). "The increase in glutaminase in hyperammonemia is associated with increased production and extracellular levels of glutamate, increased amount, and reversal of the function of the GABA transporter GAT-3, increased extracellular GABA in the cerebellum and motor in-coordination." (PMID 32917219, 2020). "Increased glutaminase activity of liver, kidney and small intestine is also involved in hyperammonemia." (PMID 32523059, 2020). "Increased membrane expression of TNFR1 in rats with chronic hyperammonemia leads to increased nuclear translocation of p50 subunit of NF-κB and, as a consequence, an increase of TNFα, IL1β, and glutaminase expression." (PMID 32917219, 2020). "The increase in lymphocytic glutaminase activity seen within 12 h from onset can lead to endotoxin-induced hyperammonemia." (PMID 30049989, 2018). "In rats with chronic hyperammonemia increased membrane expression of TNFR1 leads to increased nuclear translocation of NF-κB and, as a consequence, an increase of TNFα, IL1β, and glutaminase expression." (PMID 32917219, 2020). "Chronic hyperammonemia induces neuroinflammation in cerebellum, with glial activation and enhanced activation of the TNFR1-NF-kB-glutaminase-glutamate-GABA pathway." (PMID 32917219, 2020). "Although systemic hyperammonemia in patients with cancer is rather rare and generally does not exceed micromolar concentrations, ammonia accumulates in the TME reaching millimolar concentrations in consequence of the breakdown of glutamate by glutaminase." (PMID 40163355, 2025). "Yet, NH3 uptake by the muscle does not seem to be sufficient to maintain normal NH3 concentrations, as we observed hyperammonemia with no changes in the level of expression of muscle GS, glutaminase or NH3 transporters." (PMID 36466421, 2022).
depression (8 papers, 2016 to 2025). "Studies have confirmed that IL-1β can mediate glutamate overproduction and reduce serotonin reuptake by modulating mitochondria glutaminase activity, which contributes to the progress of depression." (PMID 37600668, 2023). "The 6 top blood biomarkers with the strongest overall CFE for tracking and predicting both depression and mania, hence bipolar mood disorders, after the first four steps were NRG1, DOCK10, GLS, PRPS1, TMEM161B, and SLC6A4." (PMID 33828235, 2021). "A number of individual top biomarkers are known to be modulated by medications in current clinical use for treating depression, such as by lithium (NRG1, PRPS1, CD47), antidepressants (SLC6A4, DOCK10, NRG1, CD47) and the nutraceutical omega-3 fatty acids (GLO1, SLC6A4, CD47, GLS, HNRNPDL)." (PMID 33828235, 2021).